RNU6-1055P (RNA, U6 small nuclear 1055, pseudogene)
Gene: Small nuclear RNA gene on chromosome 4 (186,501,109 to 186,501,215, forward strand). Ensembl gene ENSG00000212387.
Homologues: Orthologues: chimpanzee U6 (97% identical), macaque U6 (85% identical), rabbit U6 (75% identical), rat LOC120099048 (69% identical), pig U6 (66% identical), mouse Gm55001 (63% identical). Paralogues in human: RNU6-12P (83% identical), RNU6-13P (83% identical), RNU6-32P (83% identical), RNU6-1 (82% identical), RNU6-11P (82% identical), RNU6-17P (82% identical), RNU6-18P (82% identical), RNU6-2 (82% identical), RNU6-26P (82% identical), RNU6-37P (82% identical), RNU6-3P (82% identical), RNU6-45P (82% identical), and 1285 more.